CXCL8 (C-X-C motif chemokine ligand 8)
Diseases named in the same sentence as CXCL8 in open-access papers (continued):
Sharing a sentence is not in itself a finding about the gene and the disease.
metastatic disease (42 papers, 2002 to 2025). "Elevated CXCL8/IL-8 has been reported to correlate with high Gleason score and with AR loss in metastatic disease." (PMID 33569050, 2020). "In cohort 1, expression of stromal CXCL8 was significantly higher in patients with metastatic disease." (PMID 35879507, 2022). "Furthermore, in patients with advanced metastatic tumours, treatment with an anti-IL-8 mAb such as BMS-986253 s (NCT02536469), plus an anti-PDL-1 induced a significant reduction of CXCL8 serum levels and increased anti-tumor activity (NCT03400332)." (PMID 38900374, 2025). "In addition, MPO-DNA complexes and nucleosomes correlated with dsDNA, CitH3, MPO and CXCL8 levels and were increased in elderly patients and patients with metastatic disease at diagnosis." (PMID 37705974, 2023). "Clinical studies have confirmed that increased expression of CXCL8 is linked with tumor development, suggesting that suppression of ELR-CXC chemokines may be an important therapeutic approach for aggressive and metastatic tumors." (PMID 26087179, 2015). "In our study, high levels of CXCL8 in differentially expressed were observed in early- and advanced-stage CRC as well as in tissues of patients with nonmetastatic and metastatic tumors." (PMID 32038715, 2019).
uveitis (42 papers, 2009 to 2025). An inflammatory process affecting a part of or the entire uvea. "Studies have identified a significant association between uveitis and specific chemokines, including neutrophil chemotactic factor (CXCL8), monocyte chemoattractant protein 1, and macrophage inflammatory protein 1β, which are implicated in the disease's etiology and progression." (PMID 39611043, 2024). "Under specific conditions, CXCL8 could regulate the endothelial adhesion, chemotaxis, and activation of other leukocytes, affecting the secretion of inflammatory factors by monocytes and T lymphocytes, thereby causing local infiltration of macrophages and leading to uveitis." (PMID 39611043, 2024). "Secondly, adjunctive analysis of the CXCL13, CXCL10 and CXCL8 levels in the AH of patients with uveitis can be of value in the diagnosis and treatment of uveitis, either as part of a routine workup and assessment of the response to treatment or to confirm or refute a diagnosis of ocular syphilis." (PMID 38983560, 2022). "↓ uveitis.↓ neutrophils, T and B cells, M1 macrophages infiltration↓ TNF-α, CXCL8, and RANTES in the eye." (PMID 34868025, 2021). "Interleukin-8 (IL-8)/CXCL8, a proinflammatory chemokine, plays an important role in the pathogenesis of LPS-induced uveitis." (PMID 26609426, 2015). "In conclusion, our study showed that uveitis associated with TB featured increased aqueous levels of IL-6, CXCL2, CXCL8, CXCL9, and CXCL10, which is not typical of an active ocular TB infection." (PMID 22509092, 2012).
E. coli infection (41 papers, 2012 to 2025). "Two pathways Pathogenic Escherichia coli infection, Amoebiasis, and Cytokine-cytokine receptor interaction were associated with CXCL8." (PMID 36991484, 2023). "The expression levels of interleukin 1 b (IL1B), IL6, tumor necrosis factor a (TNFA), interleukin-8 (CXCL8), and defensin beta 2 (DEFB2) genes in the endometrium of the GE group were upregulated (p < 0.05) after E. coli infection." (PMID 40075974, 2025).
injury (41 papers, 2012 to 2025). Damage inflicted on the body as the direct or indirect result of an external force, with or without disruption of structural continuity. "In conclusion, CXCL8 may plays an important role in the occurrence and development of liver injury diseases caused by HBV infection." (PMID 36504808, 2022). "In traumatic brain injury, elevated CXCL8 levels in cerebrospinal fluids are connected to BBB damage and increased mortality." (PMID 34359826, 2021). "A previous study also confirmed that serum CXCL8 levels were significantly increased at 2, 6, and 24 hours after reperfusion in patients with limb ischemia-reperfusion injury." (PMID 28804223, 2017). "■Decreased COX-2 and CXCL-8 gene expression in human bronchial epithelial cells;■Reduced IL-6 and TNF-α pulmonary levels in a rat model of LPS-induced acute lung injury." (PMID 40298549, 2025). "The CXCL1, CXCL2 and IL-8/CXCL8 chemokines mediate neutrophil recruitment and activation via CXCR1/CXCR224–26, and reparixin has been reported to inhibit neutrophil-mediated inflammatory responses in mouse models of acute lung injury and lung transplantation." (PMID 33608602, 2021).
multiple sclerosis (41 papers, 2012 to 2026). A progressive autoimmune disorder affecting the central nervous system resulting in demyelination. "IL8/CXCL8 has been implicated in multiple diseases such as multiple sclerosis, glial fibrillary acidic protein autoimmunity, and infectious or post‐infectious syndromes including SARS‐CoV‐2 infection." (PMID 40781580, 2025). "A recent study showed high levels of CXCL8 expressed by human brain endothelial cells from patients with multiple sclerosis." (PMID 23029125, 2012). "Likewise, fumarates had differing effects on the expression of key genes that have been linked to multiple sclerosis (e.g., TNFAIP3, CXCL8, IL6, and IRF1)." (PMID 35455458, 2022). "Epstein–Barr virus (EBV) infection and various chemokines, including CCL20, CXCL8 and CXCL10 are considered to participate in the pathogenesis of multiple sclerosis (MS), and several studies point to a direct regulatory effect of EBV on the expression of these chemokines." (PMID 39125633, 2024).
prostatitis (41 papers, 2012 to 2026). An infectious or non-infectious inflammatory process affecting the prostate gland. "Hepatocytes secrete CXCL8 upon ethanol exposure, and the overexpression of human CXCL8 exacerbates alcoholic liver injury in mice." (PMID 36278756, 2022). "Upon analysis, expression of the cytokines IFNB1, IFNG (IFN-γ), TNF (TNF-α), TGFB1 (TGF-β), IL1B, IL2, IL6, CXCL8 (IL-8), and IL10 were all significantly increased in ‘mesenchymal’ lung ADC compared to ‘epithelial’ tumors." (PMID 29440769, 2018). "Plasma CXCL8 concentrations are not predictive of subclinical graft injury or of histological criteria for the minimization of immunosuppression in adult liver transplant recipients." (PMID 39877649, 2024). "While the specific role of ATF3 (activating transcription factor 3) in the suppression of PCa with PTEN (phosphatase and tensin homolog) dysfunction is meanwhile well known, the tumor suppressor function of IGF1, CXCL10, HIF1A, CXCL8, and CSF1 in prostate carcinogenesis remains to be elucidated." (PMID 36321189, 2023).
liver disease (40 papers, 2006 to 2025). "Many liver inflammatory diseases are associated with increased expression of CXCL8." (PMID 37122694, 2023). "The CXCL8 chemokine family, mainly responsible for inducing and maintaining the inflammatory state, is known for neutrophil activation and migration into the inflamed tissue, or neutrophil-mediated tissue injury, and plays an essential role in liver diseases." (PMID 36451225, 2022). "Therefore, the present study confirms the role of CXCL8 as a putative indicator of pancreatitis and liver disease." (PMID 28149283, 2016). "We analyzed the association between changes in plasma biomarkers and liver disease severity scores (LSM and HVPG) during the follow-up, but we only found a positive association (p-value <0.05) between plasma variations of PD1, IL10, CXCL10, CCL2, and CXCL8 and the change in LSM values." (PMID 34497613, 2021). "Literature and data mining found abnormal induction of chemokine (C-X-C motif) ligand 1 (CXCL1) and CXCL8 and down-regulation of CXCL2 in inflammatory liver diseases." (PMID 39619227, 2023). "We found a decrease in plasma biomarkers (PD1, PDL1, CXCL10, CXCL8, IL12p70, IL10, and TGFβ) and liver disease markers (stiffness measurement (LSM), hepatic venous pressure gradient (HVPG), and transaminases, among others)." (PMID 34497613, 2021). "Our data show an improvement in these immune and liver disease biomarkers in plasma (immune exhaustion (PD1), chemokines (CXCL10, CCL2, and CXCL8), and cytokines (IL10)) after achieving SVR with DAA therapy in HIV/HCV-coinfected individuals." (PMID 34497613, 2021). "While TNF alfa, IL-6, and IL-8 (CXCL8) are markers of the innate immune “storm” (neutrophil-related), CXCL9 and CXCL10 reflect the adaptive immune response (Th1/lymphocytic) as well as hemodynamic severity (portal hypertension)." (PMID 41373861, 2025). "However, the overall GR trend seems to be restorative in liver cells, selectively limiting the inflammatory overexpression of CXCL1 and CXCL8 while simultaneously sparing CXCL2, which is downregulated in various liver diseases but may be crucial for hepatic health." (PMID 39619227, 2023).
Crohn disease (39 papers, 2009 to 2026). A gastrointestinal disorder characterized by chronic inflammation involving all layers of the intestinal wall, noncaseating granulomas affecting the intestinal wall and regional lymph nodes, and transmural fibrosis. "Examples of disorders known to be driven by CXCL8 might include inflammatory disorders such as Crohn's disease, COPD, and ARDS; however, caution would be required to ensure impedance of neutrophil recruitment did not render subjects prone to bacterial infections." (PMID 34649250, 2022).
lymphoma (39 papers, 2010 to 2025). A malignant (clonal) proliferation of B- lymphocytes or T- lymphocytes which involves the lymph nodes, bone marrow and/or extranodal sites. "It should be noted that a previous study showed lower CXCL8 gene expression in lymphoma lymph nodes when compared to reactive lymph nodes." (PMID 36272970, 2022). "There are few studies on the expression of CXCLs in lymphoma except CXCL8 and CXCL11 in DLBCL10,11." (PMID 35181719, 2022).
bronchiectasis (38 papers, 2007 to 2025). Segmental, irreversible dilation of the bronchial tree resulting in the accumulation of secretions which leads to obstruction. "Neutrophils are the most abundant inflammatory cells in the airways of patients with bronchiectasis and are rapidly recruited from the bone marrow by several chemoattractants (such as IL-8/CXCL-8 and leukotriene B4) or proinflammatory cytokines (such as TNF-α)." (PMID 40589741, 2025). "It was suggested that intervention aimed at facilitating airway clearance of CXCL-8 and/or serine proteases may reduce airway inflammation in CF bronchiectasis." (PMID 36164329, 2022). "In general, we speculate that the curative mechanisms of BMGLF in bronchiectasis are primarily associated with the expressional regulation of inflammatory factors such as IL6, IL10, MMP9, CXCL8, MAPK1, and ICAM1." (PMID 33488758, 2021). "CXCL-8 levels were discovered to be high in both CF and non-CF bronchiectasis and comparable to COPD in neutrophilic bronchiectasis." (PMID 36164329, 2022). "By mapping drug targets to disease targets, we identified 51 common targets, including IL10, TLR2, STAT3, IL6, and CXCL8, which served to indicate putative pathways whereby BMGLF could be used to treat bronchiectasis." (PMID 33488758, 2021).
myeloma (38 papers, 2008 to 2025). "CXCL8 serum levels in patients with multiple myeloma, a cancer originating in bone marrow plasma cells, were elevated compared to healthy controls, and multiple myeloma cells upregulated CXCL8 expression in bone stromal cells." (PMID 37025604, 2023). "Increased levels of key cytokines have also been shown to progressively increase from controls to smouldering myeloma to multiple myeloma including CXCL8 (IL-8), IL-10, TNFα, IL6 and IFNγ." (PMID 28389623, 2017). "In vitro, CXCL8 promoted multiple myeloma cell survival and tumor-induced osteoclastogenesis." (PMID 37025604, 2023). "Certainly we were able to observe that SDF-1, which binds to CXCR4, and CXCL8 (IL-8) which is a ligand for CXCR1/CXCR2, are also significantly elevated in myeloma." (PMID 28389623, 2017). "It has previously been shown that IL-27 has anti-angiogenic activity by down regulating the expression of VEGF, IL-8/CXCL8 and CXCL5 in human multiple myeloma cells." (PMID 24274066, 2013).
systemic lupus erythematosus (38 papers, 2006 to 2025). An autoimmune multi-organ disease typically associated with vasculopathy and autoantibody production. "Although both cytokines were argued to be elevated in the scenario of SLE, CCL2 was regarded as an important biomarker for lupus nephritis flair, and CXCL8 for lupus associated interstitial lung diseases." (PMID 25889297, 2015). "Recruitment of neutrophils to the skin is mediated by pro-inflammatory cytokines and chemokines, such as TNF-α, IL-8, and CXCL8, which are elevated in lupus lesions." (PMID 41375587, 2025).
acute kidney injury (37 papers, 2009 to 2026). Sudden and sustained deterioration of the kidney function characterized by decreased glomerular filtration rate, increased serum creatinine or oliguria. "Take CXCL8 for a example, it was proved to recruit the neutrophils, assisting the activation of inflammatory pathways in the ischemic kidney and culminating the acute kidney injury." (PMID 37393391, 2023). "In addition, CXCL-8 was shown to be produced exclusively by this group, together with the CCL-2 molecule, which highlights these molecules as potential indicators of acute kidney injury resulting from Bothrops envenomation." (PMID 36117588, 2022).
endometritis (37 papers, 2010 to 2025). An acute or chronic, usually bacterial infectious process affecting the endometrium. "Additionally, the expression of IL1A, as well as CXCL8, was found upregulated in cows suffering from postpartum endometritis." (PMID 39858269, 2025). "Additionally, in contrast to cows with sub-clinical endometritis, the gene expression profiles of C3, CXCL8, LTF, TLR2, and TRAPPC13 were temporally changed in healthy cows’ circulating WBC during the postpartum period." (PMID 37756095, 2023). "In addition, proinflammatory substances, such as prostaglandins and cytokines, such as interleukin 1A (IL1A), interleukin 1B (IL1B), and C-X-C motif chemokine ligand 8 (CXCL8), were elevated in cows with preclinical and clinical endometritis." (PMID 36505731, 2022).
fungal infection (37 papers, 2008 to 2025). "Like CXCL8, both chemokines play significant roles in the recruitment and activation of neutrophils, which are essential for the early immune response to fungal infections." (PMID 41081505, 2025). "As CXCL8 is a key molecule required for the recruitment of neutrophils and their successful extravasation from the blood vessel system, this disrupted response to CXCL8 might explain, why the patient remained susceptible to bacterial and fungal infections throughout therapy." (PMID 32660441, 2020). "In the human intestinal mucosa, CXCL8 release of epithelial cells as found in this study will likely result in the recruitment of neutrophils, which are the first line of defense when coping with fungal infections and play an important role in preventing C. albicans dissemination from the gut." (PMID 28292985, 2017). "IL-8, or CXCL8, is a pro-inflammatory chemokine that acts as a neutrophil chemoattractant and has been studied in the context of fungal infections." (PMID 27092126, 2016). "CXCL8 and CXCL2 are critical chemokines involved in neutrophil recruitment and activation, which play a vital role in the host’s pro-inflammatory immune response to fungal infections." (PMID 41081505, 2025). "However, only CXCL8 levels were significantly high in the non-HIV histoplasmosis and pneumocystosis patients (Non-HIV-Hc, Non-HIV-Pj, and Non-HIV-Hc-Pj groups), possibly due to their association with local inflammatory reaction against these fungal infections." (PMID 34829225, 2021).
Neonatal sepsis (37 papers, 2007 to 2025). Systemic inflammatory response to infection in newborn babies. "For instance, tumor necrosis factor alpha (TNF-α), interleukin-1-beta (IL-1β), interleukin-6 (IL-6), and CXCL8 (interleukin-8) levels become rapidly and substantially increased during neonatal sepsis." (PMID 28367457, 2017).
emphysema (36 papers, 2006 to 2025). "In the pathophysiological network of COPD, IL-17 (produced by Th17/γδ T/NKT cells) drives neutrophil recruitment and activation by inducing epithelial secretion of CXCL8 and IL-6, thereby exacerbating pulmonary inflammation and emphysema formation." (PMID 41181156, 2025). "Indeed, CXCL8 is independently associated with severe COPD, notably worse airflow obstruction (FEV1% and FEV1/FVC), and with a progression of CT assessed emphysema over 5 years." (PMID 31174392, 2019). "Numerous reports linked CXCL8 to respiratory diseases like COPD, and Genentech had developed a CXCL8 neutralizing antibody that it thought might be useful therapeutically to treat respiratory diseases like emphysema, bronchitis, and COPD." (PMID 26097477, 2015). "CXCL8 is also used as a biomarker in murine models of COPD (for instance, to validate the efficiency of a ghrelin-based therapy in a murine model of emphysema)." (PMID 31174392, 2019). "The authors proposed that this difference may be attributed to the finding that CXCL-8 levels in BAL fluid distinguish between subjects with or without emphysema among current smokers." (PMID 37174678, 2023). "IL-17 may induce the secretion of CXCL8, CXCL1, CXCL5, G-CSF, and GM-CSF from airway epithelial cells, which recruit neutrophils; thus, they may also be related to airway obstruction, emphysema, and even lung cancer development (chronic inflammation) via ROS production and tissue damage." (PMID 34209651, 2021). "However, one study found BAL CXCL8 levels to be greater in smokers and COPD subjects compared to normal controls, and another study showed that BAL CXCL8 levels could distinguish current smokers with emphysema from those without emphysema." (PMID 26424214, 2015).
fibromyalgia (36 papers, 2014 to 2026). A chronic disorder of unknown etiology characterized by pain, stiffness, and tenderness in the muscles of neck, shoulders, back, hips, arms, and legs. "In the same way, IL8/CXCL8 is one of the most constantly reported inflammatory molecule increased in fibromyalgia and is correlated with the severity of symptoms." (PMID 39058143, 2024). "GROα/CXCL1 and IL-8/CXCL8 upregulations have been repeatedly documented in ME/CFS and fibromyalgia, two painful and largely overlapping conditions." (PMID 39058143, 2024).